RIPK1 (receptor interacting serine/threonine kinase 1)
Diseases named in the same sentence as RIPK1 in open-access papers (continued):
Sharing a sentence is not in itself a finding about the gene and the disease.
lymphopenia (7 papers, 2019 to 2025). Reduction in the number of lymphocytes. "We recently showed that T cell lymphopenia following RIPK1 loss is driven by TNFR1-dependent apoptosis of peripheral naive T cells." (PMID 40307618, 2025). "Loss of RIPK1 in humans is further characterized as a primary immunodeficiency, resulting in peripheral T cell lymphopenia and enhanced T cell-mediated TNF and IFNy secretion." (PMID 40307618, 2025). "In this study, we demonstrate that conditional ablation of Ripk1 in conventional T cells (Ripk1ΔCD4) causes peripheral T cell lymphopenia, as witnessed by a profound loss of naive CD4+, naive CD8+, and FoxP3+ regulatory T cells." (PMID 38734851, 2024). "In light of the cellular rescue by additional caspase-8 deletion, the reported senescent T cell phenotype following RIPK1 deficiency may be caused by the lymphopenia-induced dysbalance leading to age-related sequelae." (PMID 38734851, 2024). "Furthermore, Ripk1ΔCD4Casp8 ΔCD4 and Ripk1ΔCD4Tnfr1−/− double-knockout mice rescued the peripheral T cell lymphopenia, revealing that RIPK1-deficient naive CD4+ and CD8+ cells and FoxP3+ regulatory T cells specifically die from TNF- and caspase-8-mediated apoptosis in vivo." (PMID 38734851, 2024). "In conclusion, autosomal recessive RIPK1-deficiency is characterized by severe VEOIBD, growth failure and recurrent infections with lymphopenia in most patients, while other features such as inflammatory arthritis are more variable." (PMID 39762600, 2025). "Mice with T cell-restricted deletion of Ripk1 or inactivated RIPK1 kinase domains have severe T cell development defects and secondary peripheral lymphopenia." (PMID 37965338, 2023). "We demonstrated an unexpected role of caspase-8 auto-cleavage cooperating with RIPK3 or MLKL and RIPK1 in lymphopenia regulation." (PMID 35064213, 2022). "Consistently, myeloid bias and lymphopenia in the spleen and lymphopenia in the bone marrow were also significantly relieved in Ripk1+/−Ripk3−/−Casp8ΔE385/ΔE385 mice compared to those in Ripk3−/−Casp8ΔE385/ΔE385 mice." (PMID 35064213, 2022). "Collectively, these results demonstrate that RIPK1 dosage-dependent and RIPK1 kinase-independent scaffold function contributes to lymphopenia and myeloid bias in Ripk3−/−Casp8ΔE385/ΔE385 mice." (PMID 35064213, 2022). "We next asked whether the T lymphopenia in Tnfaip3.Ikk2ΔTCD4 mice was the result of a RIPK1 induced cell death process, by testing if kinase dead RIPK1D138N could reverse lymphopenia." (PMID 39327505, 2025). "Altogether, these data demonstrate that peripheral T cell lymphopenia due to the absence of RIPK1 scaffold function is caused by caspase-8-mediated apoptosis." (PMID 38734851, 2024). "T cell-specific deletion of Ripk1 induced peripheral T cell lymphopenia." (PMID 38734851, 2024). "Furthermore, Tradd−/− mice contain a normal lymphoid compartment, while conditional deletion of RIPK1 or FADD results in T lymphopenia in the periphery." (PMID 30741936, 2019). "Therefore, T lymphopenia in the Ripk1−/−Ripk3−/−Tradd−/− mice is counterintuitive, given that thymocytes from these TKO mice are completely resistant to TNFα-induced apoptosis." (PMID 30741936, 2019). "Importantly, the complete blood count results showed increased WBC and lymphocyte in the peripheral blood of Ripk1+/−Ripk3−/−Casp8ΔE385/ΔE385 mice compared to WT mice, suggesting that lymphopenia and myeloid bias in Ripk3−/−Casp8ΔE385/ΔE385 mice were largely alleviated by halving RIPK1 dosage." (PMID 35064213, 2022). "Altogether, our results in Ripk1ΔCD4 mice show the essential role of RIPK1 scaffold function in the homeostasis of naive CD4+ and CD8+ T cells and FoxP3+ Treg cells and in preventing T cell lymphopenia." (PMID 38734851, 2024). "Mice lacking Casp8 in T cells develop RIPK1-driven lymphoproliferative syndromes, whereas we demonstrate that the absence of Ripk1 induces caspase-8-driven lymphopenia and intestinal malignancies." (PMID 40307618, 2025).
lymphopenia (continued). "Ripk1K45A mice showed no change in peripheral T cell subsets, demonstrating that the T cell lymphopenia was due to the scaffold function of RIPK1 rather than to its kinase activity." (PMID 38734851, 2024). "In addition, Casp8ΔE385/ΔE385Ripk3−/− and Casp8ΔE385/ΔE385Mlkl−/− mice develop severe lymphopenia that can be prevented by reducing the RIPK1 dosage by half, not by RIPK1 kinase inactive mutant." (PMID 35064213, 2022). "Additionally, young Ripk1ΔCD4Casp8ΔCD4 mice showed no lymphopenia of peripheral CD4+ T cells, confirming our earlier findings that RIPK1 is required for the protection of peripheral CD4+ T cells from apoptosis." (PMID 40307618, 2025).
triple-negative breast carcinoma (7 papers, 2018 to 2025). An invasive breast carcinoma which is negative for expression of estrogen receptor (ER), progesterone receptor (PR), and human epidermal growth factor receptor 2 (HER2). "Moreover, CRISPR/Cas9-mediated deletion of MIB1 and MIB2 also sensitized the triple-negative breast cancer cell line MDA-MB-231 to TNF/TAK1i in a RIPK1-dependent manner." (PMID 29642005, 2018). "In triple-negative breast cancer (TNBC), AQP1 overabundance inhibited RIPK1-mediated necroptosis and promoted progression and metastasis." (PMID 35864548, 2022). "Biomarkers identifying which tumor types are likely to show success with Smac mimetics are limited although a recent publication suggests in triple negative breast cancer tumors, high mRNA expression of TNF, RIPK1 and STX37 are indicative of response." (PMID 33546280, 2021). "In addition, the responders of a neoadjuvant trial using LCL161 in triple-negative breast cancers exhibited high TNF-α and RIPK1 levels." (PMID 37867861, 2023).
acute pancreatitis (6 papers, 2019 to 2023). An acute inflammatory process that leads to necrosis of the pancreatic parenchyma. "In animal models of acute pancreatitis, ischemic injury, and neurodegeneration that are related to RIPK1/RIPK3 deficiency or MLKL knockout, it has been suggested that necroptosis may be a key element in triggering inflammation." (PMID 35276962, 2022). "The severity of caerulein-induced acute pancreatitis can be reduced by pharmacological inhibition of RIPK1." (PMID 37620300, 2023). "RIPK1-dependent cell death also contributes to ischemia-reperfusion-induced cardiac and kidney injury, acute pancreatitis as well as viral infection." (PMID 34862394, 2021).
Autoimmunity (6 papers, 2019 to 2025). The occurrence of an immune reaction against the organism's own cells or tissues. "Patient P1 showed a positive clinical response to IL-6 blockade using tocilizumab, a monoclonal antibody targeting IL-6R, consistent with outcomes observed in another patient with RIPK1 variant-associated autoimmunity." (PMID 41019071, 2025). "In addition to RIPK1 variants, variants of proteins that can regulate RIPK1 ubiquitination and phosphorylation, such as variants in the TNFAIP3 gene, which encodes the protein A20, are linked with autoimmunity and inflammation, and likely also contribute to irregularities of RIPK1 function." (PMID 41019071, 2025). "A recent study reported RIPK1 as a promising therapeutic target for the treatment of a wide range of human autoimmune and inflammatory diseases." (PMID 31824568, 2019). "Although RIPK1 conditional deletion animal models show autoimmunity, patients with RIPK1 deficiency have not been reported to have autoimmune symptoms." (PMID 34512655, 2021).
brain injury (6 papers, 2019 to 2025). Acute and chronic (see also brain INJURIES, CHRONIC) injuries to the brain, including the cerebral hemispheres, CEREBELLUM, and brain STEM. "In an independent study exploring ischemic brain injury, Nec—1, a selective inhibitor of RIPK1 kinase activity, was found to inhibit RIPK3/MLKL—dependent necroptotic signaling by impeding RIPK1 phosphorylation at Ser166." (PMID 40877572, 2025).
influenza (6 papers, 2019 to 2025). An acute viral infection of the respiratory tract, occurring in isolated cases, in epidemics, or in pandemics; it is caused by serologically different strains of viruses (influenzaviruses) designated A, B, and C, has a 3-day incubation period, and usually lasts for 3 to 10 days. "Necroptosis, mediated by RIPK1 and RIPK3, is a significant contributor to tissue damage during influenza infections." (PMID 39591329, 2024). "In influenza-infected alveolar epithelial type I (LET1) cells, ZBP1 is capable of activating RIPK1." (PMID 39591329, 2024).
lung adenocarcinoma (6 papers, 2020 to 2025). A carcinoma that arises from the lung and is characterized by the presence of malignant glandular epithelial cells. "Pazopanib could target RIPK1 to act as a cytostatic inhibitor of necroptosis, while the c-Src inhibitor Dasatinib could enhance necroptosis in paclitaxel-treated lung adenocarcinoma cells." (PMID 37600653, 2023). "In lung adenocarcinoma, the deubiquitinated protein OTUD6B promotes tumor progression by stabilizing RIPK1." (PMID 40170095, 2025).
neuroblastoma (6 papers, 2015 to 2023). Neuroblastoma (NB) is the most common solid, extracranial childhood tumor. "Consistent with our results, it was reported that Sendai virus induces RIPK1-dependent necroptosis in human neuroblastoma cells by increasing the cytoplasmic Ca2+ concentration and phosphorylation of CaMKII." (PMID 34668777, 2022). "In this study, we explored the role of RIPK1 in the SH‐SY5Y human neuroblastoma cells treated with Aβ 1–40 or Aβ 1–42." (PMID 35106914, 2022).
retinal degeneration (6 papers, 2017 to 2026). Degeneration of the retina. "Through protein–protein interaction (PPI) network analysis, six hub ferroptosis-related genes (Jun, Stat3, Hmox1, Atf3, Hspa5 and Ripk1) are ultimately identified in a mice model of retinal degeneration induced by light damage." (PMID 40299661, 2025). "Accordingly, RIPK1 inhibitor blocks microglia necroptosis and microglia-mediated inflammation, preventing retinal degeneration." (PMID 39872161, 2022). "It has been shown that RPE cells undergo necroptosis rather than apoptosis in a mouse model of oxidative stress-induced retinal degeneration, which can be block by RIPK1 inhibitor or silencing of RIPK3." (PMID 39872161, 2022). "RIPK1 inhibitor could prevent RPE cells from necroptosis in retinal degeneration." (PMID 34977874, 2021). "Some studies have shown that application of the RIPK1 inhibitor Nec1 was sufficient to reduce cell death in some, but not other, retinal degeneration models." (PMID 28842607, 2017).
ZIKV infection (6 papers, 2020 to 2025). "In Zika virus infection of neurons, receptor interacting protein kinase 1 (RIPK1) and RIPK3 signaling suppresses viral replication via IRG1-mediated ITA production." (PMID 37261340, 2023). "To confirm that necroptosis was induced, we next pre-treated the U251 cells with necrostatin-1, an inhibitor of RIPK1, followed by ZIKV infection." (PMID 33796483, 2021). "In this study, we uncover that RIG-I, a cytoplasmic dsRNA sensor, can recruit caspase-8, RIPK1, ASC, caspase-1, and NLRP3, forming a more complex PANoptosome to activate PANoptosis following ZIKV infection." (PMID 41263557, 2025). "We further elucidated that ZIKV infection drives PANoptosome formation, with RIG-I nucleating the complex by recruiting ASC, caspase-1, NLRP3, caspase-8, and RIPK1 to activate PANoptosis." (PMID 41263557, 2025).
epilepsy (5 papers, 2023 to 2025). A brain disorder characterized by episodes of abnormally increased neuronal discharge resulting in transient episodes of sensory or motor neurological dysfunction, or psychic dysfunction. "Through this screening process, we identified the anti-epilepsy drug phensuximide (Phen) as a novel inhibitor of RIPK1 kinase activity." (PMID 40456737, 2025). "Our results confirmed changes in ZBP1, GSDMD, and RIPK1 expression during epilepsy onset, further supporting the potential involvement of PANoptosis in seizure pathogenesis." (PMID 38404827, 2024). "In this study, we then assessed the mRNA of ZBP1, GSDMD, and RIPK1 and the protein expression of ZBP1 and RIPK1 in epilepsy models in vitro." (PMID 38404827, 2024). "We observed a significant increase in the mRNA expression of ZBP1, GSDMD, and RIPK1 in the peripheral blood of newly diagnosed seizure patients compared to age-matched healthy children (P < 0.01), suggesting their involvement in epilepsy onset." (PMID 38404827, 2024). "We also conducted various experiments to validate the expression changes of three PANoptosis markers (ZBP1, GSDMD, and RIPK1) during the pathophysiological process of epilepsy." (PMID 38404827, 2024). "Upregulated miR-494-3p inhibits the expression of receptor-interacting serine/threonine-protein kinase 1 (RIPK1) in epilepsy rats, which is a necroptosis regulator." (PMID 36835100, 2023). "Additionally, we assessed the mRNA of ZBP1, GSDMD, and RIPK1 and the protein expression of ZBP1 and RIPK1 in epilepsy models in vitro." (PMID 38404827, 2024). "Importantly, phensuximide, which has already been approved by the FDA for the treatment of epilepsy, effectively prevents the kinase activity of RIPK1 without affecting the NF-κB and MAPK pathways." (PMID 40456737, 2025).
heart failure (5 papers, 2019 to 2024). Inability of the heart to pump blood at an adequate rate to meet tissue metabolic requirements. "Our data also demonstrated that aberrant RIPK1 kinase activation is a key effector driving myocardial apoptosis and necroptosis in vivo, which underlies cardiac remodeling and heart failure induced by TAB2 deficiency." (PMID 34990405, 2022). "For example, the knockout of RIPK3 endowed the mice with the ability to resist heart failure that was triggered by ischemia/reperfusion, and this was independent of the activation of RIPK1 or MLKL." (PMID 31248365, 2019).
Nephropathy (5 papers, 2017 to 2022). A nonspecific term referring to disease or damage of the kidneys. "We previously reported that two RIPK1 inhibitors, Cpd-71 and wogonin, attenuated cisplatin-induced nephropathy and were superior to the classical RIPK1 inhibitor Nec-1." (PMID 36408256, 2022). "RIPK1 kinase-deficient (KD) mice, RIPK3−/− mice, and/or treatment with Nec-1 all showed nephroprotective effects in almost all forms of kidney injuries, which confirms that necroptosis plays a critical role in the development of renal diseases." (PMID 36361505, 2022). "Several studies have observed the role of necroptosis (e.g., higher RIPK1, RIPK3, and MLKL expression and/or phosphorylation levels) in different forms of kidney disease." (PMID 36361505, 2022). "Additionally, disruption of Smad2 also reduced RIPK1 and RIPK3, the central regulators in necroptosis in cisplatin nephropathy." (PMID 31754396, 2019).
non-alcoholic steatohepatitis (5 papers, 2020 to 2025). "The receptor-interacting protein (RIPK1) promotes cell death and contributes to nonalcoholic steatohepatitis pathogenesis." (PMID 36414671, 2022). "We propose that deSUMOylation of RIPK1 by SENP1 provides a pathophysiologically relevant cell death-restricting checkpoint that modulates RIPK1 activation in the pathogenesis of nonalcoholic steatohepatitis." (PMID 36414671, 2022). "RIPK1 is SUMOylated at K550, and the SUMOylation of RIPK1 promotes its activation, which is reversed by SUMO-specific protease 1 (SENP1), inhibiting cell death and the development of non-alcoholic steatohepatitis." (PMID 40305291, 2025).
Obesity (5 papers, 2023 to 2025). Accumulation of substantial excess body fat. "These obesity-associated polymorphisms in the RIPK1 gene functionally result in elevated RIPK1 expression in adipose tissue in humans, and elevated RIPK1 expression in mice." (PMID 36175539, 2023). "Although the role of upstream kinases RIPK1 and RIPK3 in obesity and MAFLD remain debatable, there are numerous reports that MLKL deficiency protects mice from MAFLD." (PMID 39532538, 2025). "Additionally, genes involved in white fat differentiation and adipogenesis pathways were downregulated by OJ consumption, including KLF4 (−2.3), RIPK1 (−1.7), PLIN2 (−1.99), and CXCL8 (−34.43); genes found as overexpressed in obesity." (PMID 41169019, 2025). "Importantly, RIPK1 inhibition has shown efficacy not only in prophylactic interventions but also in established MASLD, reducing obesity and triglyceride accumulation in the liver." (PMID 38195700, 2024).
pancreatitis (5 papers, 2019 to 2025). Inflammation of the pancreas. "Inhibiting RIPK1 activity in the pancreatic cells that produce digestive enzymes significantly reduced the necrosis and associated damage found in pancreatitis." (PMID 31375658, 2019). "The results suggest, however, that drugs controlling RIPK1 activity and its associated signaling pathway may be useful for treating pancreatitis and preventing it from becoming life-threatening." (PMID 31375658, 2019). "In pancreatitis, the death of acinar cells can be prevented by silencing RIPK1, thereby reducing the severity of pancreatitis." (PMID 40229837, 2025). "By targeting RIPK1-driven necroptotic pathway, Vemurafenib alleviated TNFα-induced systemic inflammation and caerulein-induced pancreatitis in murine disease models." (PMID 37620300, 2023). "Gang Wang and colleagues at the First Affiliated Hospital of Harbin Medical University, in China investigated the activity of the protein RIPK1 in pancreatitis in rats." (PMID 31375658, 2019). "The authors showed that in mice bearing a mutation in the RIPK1 kinase domain a germline deficiency of the RIPK1 kinase domain or of RIPK3 were not rescued from cerulein-induced pancreatitis." (PMID 37409125, 2023). "A study on pancreatitis suggested that the RIPK1/NF-κB/AQP8 axis may inhibit acinar cell necrosis." (PMID 37378023, 2023).
renal fibrosis (5 papers, 2020 to 2025). A final common manifestation of a wide variety of chronic kidney diseases characterized by glomerulosclerosis and tubulointerstitial fibrosis. "In rat noninflammatory subtotal nephrectomy model of CKD, necroptosis contributes to the progressive loss of renal tubule cells, thereby aggravating renal fibrosis and promoting the progression of CKD, which can be alleviated by RIPK1 inhibitor." (PMID 39872161, 2022). "Our UUO mouse model showed that a single injection of Nec-1 (inhibitor of RIPK1) ameliorated kidney injury, release of proinflammatory cytokines (IL-1β and TNF-α) and a chemokine (MCP-1), and renal fibrosis." (PMID 33390935, 2020). "Furthermore, we found that treatment with RIPK1 inhibitor, Nec-1 significantly inhibited the activation of the RIPK1/RIPK3/MLKL signaling pathway, ameliorated renal dysfunction, and reduced kidney inflammation and renal fibrosis." (PMID 36756299, 2023).
Splenomegaly (5 papers, 2019 to 2024). Abnormal increased size of the spleen. "Myeloid cell-specific inhibition of TBK1 and IKKε caused splenomegaly, neutrophilia, and monocytosis that were dependent on RIPK1 kinase activity, demonstrating that TBK1 and IKKε function in a cell-intrinsic manner to suppress RIPK1-dependent expansion of myeloid cells." (PMID 38167258, 2024). "As expected, no signs of inflammation were observed in the mice reconstituted with Ripk1+/+ bone marrows, whereas mice reconstituted with Ripk1Y383F/Y383F bone marrows showed splenomegaly alone with massive infiltration of neutrophils in the spleen." (PMID 36329033, 2022). "Ripk1K612R/K612R mice are viable, but develop age-dependent reduction of RIPK1 expression, spontaneous intestinal inflammation and splenomegaly, which can be rescued by antibiotic treatment and partially by Ripk3 deficiency." (PMID 33311474, 2020). "Although Abin1Q478H/Q478H cells are sensitive to RIPK1 kinase–RIPK3–MLKL‐dependent necroptosis, only anemia and splenomegaly are alleviated by RIPK3 deficiency but not by MLKL deficiency or the RIPK1 kinase‐dead mutation." (PMID 38009796, 2024).